IL13RA2 (interleukin 13 receptor subunit alpha 2)
Diseases named in the same sentence as IL13RA2 in open-access papers (continued):
Sharing a sentence is not in itself a finding about the gene and the disease.
glioma (continued). "The CAR‐T cells produced large and approximately equal amount of IFN‐γ in the supernatant when cultured with IL‐13Rα2 positive glioma cell lines." (PMID 38685487, 2024). "In a large trial of patients with recurrent high-grade gliomas, IL-13Rα2-targeting CAR-T cells were feasible to manufacture and well tolerated when delivered via intratumoral and/or intraventricular routes." (PMID 38454126, 2024). "Clone 14‐1 migrated to IL‐13Rα2Fc and cell free supernatants only from IL‐13Rα2+ve confluent glioma tumour cells in a chemotaxis assay." (PMID 38685487, 2024). "In particular, monoclonal antibodies specific for IL-13Rα2, which disrupt IL-13/IL-13Rα2 interactions, improved the survival of mice with orthotopic glioma xenografts and inhibited liver metastasis of colorectal cancer cells expressing IL13Rα2." (PMID 39598436, 2024). "In glioma, expression of IL13Ra2 is distinct among gliomas with different molecular subtypes and WHO malignancy grade and positively correlates with tumor proliferation and invasion and immune evasion abilities, leading to poorer patient outcomes." (PMID 38201655, 2024). "Clinical trials have explored the use of peptide-pulsed dendritic cells (DCs) as a cancer vaccine for advanced glioma patients, targeting IL-13Rα2." (PMID 38612592, 2024). "Combining certain inorganic nanoparticles with IL13Ra2 antibodies demonstrates targeted anti-glioma activity against glioma cells; such strategies include high-performance nano-biocatalysts and biocompatible magnetic vortex discs." (PMID 38201655, 2024). "In the in vivo study, tumor volume in the mice implanted with EGFRvIII+ and IL-13Rα2+ glioma cells increased significantly in comparison with the mice implanted with WT epidermal growth factor receptor (EGFR) glioma cells." (PMID 38339374, 2024). "The survival rate of patients with EGFRvIII+ glioma and high IL-13Rα2 expression was significantly lower than that of patients with low IL-13Rα2 expression." (PMID 38339374, 2024). "The expression of IL-15, for instance, improved the persistence and proliferative capacity of IL-13Rα2-CAR-T cells in a preclinical glioma model and, thus, led to a stronger anti-tumor activity." (PMID 37443804, 2023). "IL13Rα2 is expressed on both adult and pediatric brain tumors, including high-grade glioma, ependymoma, atypical teratoid/rhabdoid tumor, and brainstem glioma." (PMID 36968221, 2023). "Many possible therapeutic targets, such as vascular endothelial growth factor (VEGF) and IL-13 receptor α2 (IL-13Rα2), have been discovered, as the mechanistic research probes deeper to elucidate the nature of glioma." (PMID 37444531, 2023). "Evidence of transient anti-glioma activity was observed with necrosis on MRI, and down-regulation of IL13Rα2+ expression in GBM, following treatment." (PMID 37568717, 2023). "In terms of tumor antigens used for pulse, glioma‐associated antigens (GAA) can be selected, such as WT1, TRP2, and IL‐13Rα2, or glioma‐specific antigen (GSA) EGFRvIII, while different antigen stimuli have discrepancy effects on DC function." (PMID 36464889, 2023). "BiKE facilitates the engagement of NK cells and glioma cells, directs NK cell-mediated cytotoxicity of IL13Ra2-positive gliomas, and extends the survival of GBM-bearing animals." (PMID 37443750, 2023). "The specificity for IL13Rα2 (which is glioma-restricted) over the more broadly expressed IL13Rα1 is driven by a point mutation (E13Y) that gives a 50-fold higher affinity for IL13Rα2 and a 5-fold lower affinity for IL13Rα1/IL4Rα over wild-type IL13." (PMID 37846297, 2023). "Over 30 variations of treatments focused on IL-13Rα2 have been used to target and kill glioma cells in vitro, and in preclinical clinical settings." (PMID 37158824, 2023). "The vaccine was pulsed with class I peptides from six tumour-associated antigens (TAA) of AIM-2, MAGE1, TRP-2, gp100, HER2/neu and IL-13Rα2, which are expressed on gliomas and over expressed in their cancer stem cell population." (PMID 37304305, 2023).
glioma (continued). "Overall, BiKE can activate NK cells and induce the killing of glioma cells with various expression levels of the target IL13Rα2." (PMID 37443750, 2023). "Research of Wang indicated that Pep-1 can invade glioma tumor cell nuclei via IL-13Rα2-mediated endocytosis." (PMID 36744246, 2023). "This study reports the design, generation, and functional analysis of therapeutic BiKE targeting for IL13Ra2-positive gliomas." (PMID 37443750, 2023). "The labeled and non-labeled CAR-T cells produced large and equal amount of IFN-γ in the supernatant when cultured with IL-13Rα2 positive glioma cell lines." (PMID 37286997, 2023). "In the orthotopic glioma xenograft mouse model, IL13Rα2 CAR T cells that were also designed to express IL-15 exhibited elevated anti-glioma activity, enhanced persistence, and considerably longer survival than the control." (PMID 36721153, 2023). "To assess the protein expression and status of IL-13Rα2 and FUS in clinical glioma samples, we performed immunostaining with anti-IL-13Rα2 and anti-FUS." (PMID 37158824, 2023). "Here, we described a BiKE molecule that successfully targets IL13Ra2-positive gliomas even with low receptor expression, albeit at a lesser degree than high-expressing IL13Ra2-positive gliomas." (PMID 37443750, 2023). "In conclusion, we demonstrate that a BiKE generated in a mammalian expression system is functional in augmenting NK cell targeting of IL13Rα2-positive gliomas." (PMID 37443750, 2023). "Since the BiKE molecule showed the greatest glioma killing in vitro with high receptor expression, we sought to test survival benefits in two xenograft models with high-expression levels of IL13Rα2, both GBM6 and GBM12." (PMID 37443750, 2023). "Several preclinical studies were performed in orthotopic glioma mouse models with CD8+ CAR-T cells that targeted IL-13Rα2, including a CAR construct that was optimized with a 4-1BB co-stimulatory domain." (PMID 37443804, 2023). "CAR-T cell therapy paved the way for a novel approach in cancer therapy; several CARs have been established against gliomas by targeting IL13Rα2, EGFRvIII, HER2, and CD70." (PMID 36146527, 2022). "Chimeric antigen receptors (CARs) also paved the way for a novel approach to cancer therapy; several CARs have been established against gliomas by targeting IL13Rα2, EGFRvIII, HER2, and CD70." (PMID 36146527, 2022). "IL-15 co-expression was also used in a model of IL-13Rα2-positive glioma (IL-13Rα2-CAR.IL-15 T cells) and results showed better in vivo persistence and greater antiglioma activity." (PMID 35211124, 2022). "The patient-derived primary GBM tumor line PBT030-2 and human glioma line U251T endogenously express IL13Rα2 at high levels, consistent with its overexpression in pathological conditions." (PMID 35939683, 2022). "CARs using IL13 mutants for targeting IL13Rα2 have previously shown efficacy in both preclinical (8, –10) and clinical glioma." (PMID 35939683, 2022). "Pep-1 was used for efficient crossing of BBB and home to glioma cells through IL13Rα2 mediated endocytosis." (PMID 35612318, 2022). "IL-13RA2-CAR.IL15 T cells recognize glioma cells, are more proliferative, and produce more cytokines, thus exhibiting more potent anti-tumor activity." (PMID 36466873, 2022). "Up to now, well-studied CAR-T cell therapy targets in glioma include IL13Rα2, EGFRvIII, HER2, and GD2." (PMID 36261831, 2022). "Targeting glioma-specific antigens such as EGFRvIII, IL13Rα2, and HER2 also showed anti-glioma effects in mouse models." (PMID 35982954, 2022). "Co-expression of HER2- and IL-13Rα2-specific CARs enhanced T cell functionality against autologous glioma cells." (PMID 35464460, 2022). "Interleukin-13 receptor α2 (IL-13Rα2) was identified as a glioma specific marker, and CAR-T therapy with cells targeting this protein was evaluated in a clinical trial." (PMID 34168976, 2021).
glioma (continued). "Interleukin-13 receptor α2 (IL13Rα2) is a promising target due to its abundant and specific expression in MG relative to low-grade glioma or normal brain tissue." (PMID 34819930, 2021). "Although based on tentative classification of expression level, the authors found that IL13Rα2 is weakly expressed in low-grade gliomas other than MG." (PMID 34819930, 2021). "Some of the TAAgs tested in glioma, survivin, WT-1 protein, EphrinA2, and IL13RA2, have been investigated as potential peptide vaccines (NCT04013672, NCT03149003, NCT02078648); however, therapeutic efficacy has been limited." (PMID 34084145, 2021). "For example, IL-13Rα2 is overexpressed on glioma cells, therefore it is an attractive target for peptide-modified nanotherapies." (PMID 33790740, 2021). "We focused on IL13RA2 as this gene encodes a monomeric IL4-independent and high grade glioma-associated IL13 receptor." (PMID 34447744, 2021). "Another novel strategy used to target recurrent glioma is based on the differential expression of the IL-13 receptor by GBMs (IL13Rα2) that differs from the physiological IL4R/IL13R receptor expressed by normal cells." (PMID 34084145, 2021). "Similar to pancreatic cancer, two AP-1 transcription factors, c-jun and Fra-1, played an important role in the IL-13Rα2 signaling in human glioma samples." (PMID 34201539, 2021). "IL13Rα2 CAR T cells engineered to additionally express IL-15 displayed greater anti-glioma activity and improved persistence and significantly prolonged survival of mice than control IL13Rα2 CAR T cells in orthotopic glioma xenograft models." (PMID 34113233, 2021). "This was observed via their cytolytic actions as well as the production of IFN-γ and TNF-α in the presence of IL13Rα2-positive glioma cells." (PMID 33204365, 2020). "Recent data suggested that IL-15 secretable CART and IL13Rα2-CAR.IL15 demonstrated survival advantages in U373 glioma orthotopic xenograft models compared to IL13Rα2-CAR." (PMID 33281826, 2020). "They indicated that IL13Rα2-CAR T cells had antiglioma actions in two syngeneic glioma models and produced a proinflammatory tumor microenvironment in their in vivo experiments." (PMID 33204365, 2020). "Interleukin-13 receptor alpha 2 (IL13Rα2) overexpression occurs in over 75% of GBM tumors, and is associated with invasive glioma growth and poor prognosis." (PMID 33176788, 2020). "Glioma homing peptides (Pep-1) specifically bind the overexpressed interleukin-13 receptors α2 (IL-13Rα2) on glioma cells." (PMID 33007959, 2020). "The Pep-1 is a specific ligand for interleukin-13 receptor α2 (IL-13Rα2), which is overexpressed in established glioma cell lines, enabling mediated endocytosis of glioma cells." (PMID 31979318, 2020). "Overexpression of interleukin-13 receptor α2 (IL13Rα2) is observed in several cancer types including glioma and pancreatic cancer." (PMID 30718742, 2019). "In a glioma model, an IL13Rα2 specific CAR T cell that also had transgenic expression of IL-15 successfully killed tumor, proliferated, and produced cytokine in vivo; however, recurrent tumors demonstrated IL13Rα2 downregulation." (PMID 30804938, 2019). "Recently, trivalent peptide vaccines targeting glioma-restricted antigens, including EphA2, IL13rα2, and survivin, have been proven to be safe and feasible for the treatment of pediatric GBM." (PMID 31783889, 2019). "In this regard, IL-13Rα2-CAR T cells modified to secrete IL-15 (IL-13Rα2.IL-15-CAR) demonstrated superior proliferative capacity and antitumor activity in vitro and in vivo against high grade glioma compared to IL-13Rα2-CAR alone." (PMID 30828333, 2019). "For solid tumors, a CAR specific for both HER2 and MUC1 had promising in vitro results in a breast cancer model, and a dual-target CAR specific for HER2 and IL13Rα2 showed greater success than single-target CARs in a xenograft glioma model." (PMID 30804938, 2019).
glioma (continued). "Studies have also used CD28 with dual CARs, such as HER2/MUC1 bispecific CARs in in-vitro breast cancer models and HER2/IL13Rα2 CARs in xenograft glioma models." (PMID 30804938, 2019). "Since IL13Rα2 inhibition as a target in glioma therapy proved ineffective, further investigation of the IL13Rα2 signaling and its role in glioma progression needs to be investigated." (PMID 31561550, 2019). "Several studies have demonstrated that overexpression of interleukin-13 receptor α2 (IL13Rα2) can be found in a variety of human cancer cells such as colorectal, glioma, squamous cell carcinoma of head and neck, and AIDS-associated Kaposi’s sarcoma." (PMID 31878102, 2019). "C-Jun and Fra-1 transcription factors bound to nuclear fractions isolated from IL-13Rα2 positive IL-13 treated glioma cell lines (U251 and A172) compared to untreated cell lines at highly statistically significant level (P = 0.0018)." (PMID 30572904, 2018). "An scFv fragment of an anti-IL13Rα2 (a selective marker of glioma) mAb was fused in place of the fiber-knob with a T4-fibritin trimerization motif between the scFv and shaft." (PMID 29904022, 2018). "Herein, we have investigated a role of IL-13/IL-13Rα2 axis in signaling through AP-1 transcription factors in human glioma samples in situ." (PMID 30572904, 2018). "This delivery system introduced taxol to the brain via endocytosis of the interleukin-13 receptor subunit alpha-2 (IL-13RA2), which showed elevated expression in gliomas (Patent application: CN103655517 A)." (PMID 30135644, 2018). "An in-depth investigation of the mechanism of interaction of the IL13 conjugated nanoliposomes with glioma tumors expressing IL13Rα2 and their ability to overcome the known drug resistance properties was described in our earlier study." (PMID 29304038, 2018). "Similar to in vitro results, we demonstrated that IL-13Rα2 are overexpressed in glioma surgical specimens in situ and AP-1 transcription factors are constitutively activated without exogenous administration of IL-13." (PMID 30572904, 2018). "c-Jun and Fra-1 were only two transcription factors that were consistently induced by IL-13 in IL-13Rα2 positive glioma cell lines." (PMID 30572904, 2018). "With this modification in antigen specificity, scFv-based IL13Rα2 CARs induce tumor regression in mouse xenograft models of glioma and show insignificant recognition of IL13Rα1 receptors." (PMID 30031396, 2018). "Krenciute, G.; Krebs, S.; Torres, D.; Dotti, G.; Lesniak, M.S.; Balyasnikova, I.V.; Gottschalk, S. Charachterization and functional analysis of scFv-based CARs to redirect T cells to IL13Rα2-positive glioma." (PMID 30400835, 2018). "We examined the activation of AP-1 family of transcription factors (c-Jun, Fra-1, Jun-D, c-Fos, and Jun-B) after treating U251, A172 (IL-13Rα2 +ve) and T98G (IL-13Rα2 −ve) glioma cell lines with IL-13 by RT-qPCR, and immunocytochemistry (ICC)." (PMID 30572904, 2018). "Whilst the resultant virus selectively infected glioma cells based on IL13Rα2 expression, the production process demonstrates the difficulty obtaining such a stable scFv." (PMID 29904022, 2018). "There are currently two clinical trials, one initiated in 2015 and one in 2018, testing the efficacy and safety of IL13Rα2 directed CAR T cells against glioma patients." (PMID 30031396, 2018). "When IL-13Rα2 expression was compared between lower-grade glioma and high-grade GBM, both IL-13Rα1 and IL-13Rα2 gene expression levels were significantly lower in lower-grade glioma compared with GBM." (PMID 29168083, 2018). "We demonstrate here that expression of sIL15 or mbIL15 in IL13Rα2-CAR T cells enhance their anti-glioma activity." (PMID 30400835, 2018). "For example, a peptide-based vaccine plus poly-ICLC for low-grade gliomas using four targets (IL-13RA2, EphA2 receptor, Wilms tumor 1 and survivin) was well tolerated in patients with grade II glioma." (PMID 30366424, 2018).
glioma (continued). "IL-13Rα2-targeting CARTs have been shown to selectively target and kill IL-13Rα2-positive tumor cells in vitro and in vivo, producing regression of xenograft glioma tumors in a murine model." (PMID 30386740, 2018). "Affinity pull-down assay showed that the level of GTP-bound Ras proteins was marked enhanced in glioma cells co-expressing IL-13Rα2 and EGFRvIII when compared to EGFRvIII alone or IL-13Rα2 alone." (PMID 29203859, 2017). "The CARs in current studies are led by scFv against five antigens (HER-2, EGFRvIII, MUC-1, IL13Rα2, and EphA2), specific for antigens expressed on glioma cells and/or other solid tumors." (PMID 28993773, 2017). "The results showed that human glioma cells co-expressing IL-13Rα2 and EGFRvIII exhibited a higher growth rate compared to EGFRvIII-positive cells." (PMID 29203859, 2017). "In immunodeficient mice bearing subcutaneous glioma tumors, anti-IL-13Rα2(scFv)-PE38 demonstrated significant antitumor activity with a MTD of 200 mg/kg when given intraperitoneally twice daily for 5 days." (PMID 28752098, 2017). "IL-13Rα2, type I internalized plasma membrane receptor, is abundantly expressed in established glioma cell lines and primary GBM cell cultures." (PMID 28933201, 2017). "IL13RA2 is a tumor-restricted receptor found to be present in several aggressive malignancies, including in the vast majority of high-grade gliomas and malignant melanoma." (PMID 28881623, 2017). "Histological analysis of IL-13Rα2-positive glioma tumor brain sections showed infiltrating tumor cells invading into normal brain parenchymal (as indicated by the red arrow)." (PMID 29203859, 2017). "The anti-IL-13Rα2(scFv)-PE38 is highly cytotoxic to U251 glioma and other cancer cell lines in vitro." (PMID 28752098, 2017). "Pep-1 (Cys-Gly-Glu-Met-Gly-Trp-Val-Arg-Cys) functions as a BBTB-penetrating and glioma targeting peptide by specifically binding to interleukin-13 receptor-α2 (IL-13Ra2) with high affinity, followed by internalization into glioma cells." (PMID 28933201, 2017). "The Pep-NP exhibited enhanced uptake by C6 glioma cells in vitro and accumulation in glioma-bearing brain in vivo through IL-13Rα2 mediated endocytosis." (PMID 26567528, 2015). "Collectively, the in vitro assays demonstrate that Ad5FFscFv47-CMV-GFP specifically infects IL13Rα2-expressing glioma cells." (PMID 26656559, 2015). "Based on the high affinity with IL-13Rα2, Interleukin-13 (IL-13) has been used as a ligand in glioma trials of immunotoxin therapy for GBM11." (PMID 26567528, 2015). "Pep-NP-PTX, relied on Pep-1 which has high affinity with IL-13Rα2 overexpressed on the surface of C6 glioma cells, achieved the highest PTX accumulation in the glioma site." (PMID 26567528, 2015). "Our results validate scFv47 as a highly selective IL13Rα2 targeting agent and confirm that it can be utilized for the redirection of adenoviral tropism to cancer and cancer stem-like glioma cells." (PMID 26656559, 2015). "To further validate the ability of Ad5FFscFv47-CMV-GFP to transduce neurospheres derived from the of IL13Rα2-expressing glioma cells, we analyzed patient derived primary glioma cells GBM39 and GBM43." (PMID 26656559, 2015). "Our data validate scFv47 as a highly selective IL13Rα2 targeting agent and justify further development of scFv47-modified oncolytic adenovirus and other therapeutics for the treatment of IL13Rα2-expressing glioma and other malignancies." (PMID 26656559, 2015). "Based on interleukin-13 receptor α2 (IL-13Rα2) over-expression on glioma cell, it was demonstrated to be a potential receptor for glioma targeting." (PMID 26567528, 2015). "The Ad5FFscFv47-CMV-GFP infectivity was well correlated with the level of IL13Rα2 expression on the cell surface in all studied glioma cell lines." (PMID 26656559, 2015).